PIR (pirin)
Diseases named in the same sentence as PIR in open-access papers (continued):
Sharing a sentence is not in itself a finding about the gene and the disease.
melanoma (19 papers, 2010 to 2025). A malignant, usually aggressive tumor composed of atypical, neoplastic melanocytes. "Here, we have analyzed the diagnostic and prognostic value of Pirin expression in the early stages of melanoma, and its role in the biology of melanocytic cells." (PMID 37308689, 2023). "Pirin is implicated in several cellular activities including cell cycle and inflammatory responses, and has been suggested to be a marker of melanoma prognosis." (PMID 37762086, 2023). "According to the TCGA database, high expressions of PIR were significantly associated with short overall survival in glioblastoma, low‐grade glioma, and melanoma patients." (PMID 30444038, 2019). "Pirin was also demonstrated to be associated with metastasis of melanoma and cervical cancer cells." (PMID 38033031, 2023). "This search for early prognostic factors in melanoma is one of our main research objectives, and here we focused on studying Pirin expression as an early diagnostic and prognostic marker of melanoma, as well as its role in the cellular mechanisms driving melanoma progression." (PMID 37308689, 2023). "Furthermore, several reports have implicated pirin as an important factor in cancer cell proliferation, migration, and tumour progression in the context of melanoma, breast, lung, cervical, prostate, and oral cancer." (PMID 35204145, 2022). "However, there is an interaction between Pirin, B-cell lymphoma 3-encoded protein (BCL-3), and Slug in melanoma cells, whereas in cervical cancer cells Pirin induces EMT by decreasing E-cadherin expression independent of BCL-3-Slug signaling." (PMID 33557375, 2021). "In this report we show that an abnormal pattern of PIR sub-cellular localization is a characteristic feature of a subset of melanomas, and suggest it may represent a marker associated with disease progression." (PMID 20089166, 2010). "However, since our data from early primary melanomas was heterogeneous, one might expect that other potential risk factors might be masking the association between Pirin expression and the probability of metastasis." (PMID 37308689, 2023). "Discrepancies among results may be linked to the tumor type or origin as role of Pirin in EMT-linked increase on migration capacity has been observed in tumors of epithelial origin while melanoma arises from the malignant transformation of neural crest-derived non-epithelial cells." (PMID 37308689, 2023). "Recent mechanistic investigations have clarified that pirin acts as a transcriptional co-regulator in melanoma cells, directly engaging with MRTF-A (myocardin-related transcription factor A)." (PMID 40740997, 2025). "While Pirin was identified as the direct target, its precise mechanism in melanoma cells needs deeper elucidation, particularly regarding its role in proliferation and apoptosis." (PMID 40740997, 2025). "Results of the molecular docking study shed light on pirin as a possible target for the anti-melanoma activity of azelaic acid." (PMID 38909081, 2024). "Accordingly, when we analyzed the amounts of Pirin protein, less Pirin was evident in all the melanoma cell lines analyzed relative to the melanocytes." (PMID 37308689, 2023). "The differences in Pirin expression observed between benign and malignant lesions, as well as in the cell lines, suggested a need to assess the biological processes regulated by Pirin in the context of melanoma." (PMID 37308689, 2023). "In melanocyte context, a homogenously high Pirin expression in benign melanocytes from nevi was observed, in contrast to the heterogeneous expression in malignant melanomas." (PMID 37308689, 2023). "As such, MeWO and A2058 melanoma cells were transfected with a plasmid to overexpress PIR, and, essentially biological processes in cancer progression such as migration and cell proliferation were analyzed." (PMID 37308689, 2023).
melanoma (continued). "In a retrospective study, we have also demonstrated the relationship between RKIP and Pirin protein expression in melanoma biopsies and malignant progression." (PMID 37046835, 2023). "To further study the role of Pirin in the pathogenesis of melanoma, we evaluated the expression of Pirin in melanocytes and eleven melanoma cell lines by RT-qPCR and in Western Blots." (PMID 37308689, 2023). "The nuclear localization of Pirin contradicts such role, but presence of Pirin in cytoplasm in a subset of melanomas has been reported previously." (PMID 38033031, 2023). "Conversely, overexpression of PIR mRNA was associated with weaker LUM and THY-1 gene expression in transfected melanoma cells relative to the control cells." (PMID 37308689, 2023). "Pirin expression was analyzed in a total of 314 melanoma biopsies, correlating this feature with the patient’s clinical course." (PMID 37308689, 2023). "Significantly weaker expression of the JARID1B, E2F1 and c-MYC genes was clearly seen in melanoma cells that overexpressed Pirin relative to the control cells." (PMID 37308689, 2023). "Overexpression of PIR was verified by Western Blots, achieving a 5 to 15-fold increase in Pirin protein relative to the parental A2058 and MeWO melanoma cell lines, respectively." (PMID 37308689, 2023). "In summary, our study supports the use of Pirin staining along with the Breslow index as a prognostic marker at early stages (I–II) of melanoma." (PMID 37308689, 2023). "The immunohistochemistry multivariate analysis revealed that early melanomas with stronger Pirin expression were more than twice as likely to develop metastases during the follow-up." (PMID 37308689, 2023). "Most recently, pirin was also identified as a molecular target of a series of compounds, which have been shown to inhibit melanoma metastasis and bleomycin-induced skin fibrosis." (PMID 35204145, 2022). "By inducing PIR knockdown, it was also found that metastatic melanoma cells change both morphology and size, which was compatible with a senescent phenotype." (PMID 33557375, 2021). "Altogether, these results suggest that Pirin contributes to the metastatic properties of melanoma cells." (PMID 33557375, 2021). "It was also established that Pirin localizes in the nucleus or cytoplasm, depending on the stage of melanoma progression." (PMID 33557375, 2021). "By contrast, overexpression of PIR was involved in inhibition of cellular senescence in melanocytic cells, resulting in transformation to melanoma." (PMID 27782828, 2016). "PIR localization was subsequently analyzed in vitro in melanoma cell lines through a high content immunofluorescence based approach (ImmunoCell-Array)." (PMID 20089166, 2010). "We, therefore, investigated if PIR expression levels are modulated in other types of malignancies and found that PIR is expressed at high levels in a subset of melanomas." (PMID 20089166, 2010). "Here we demonstrate that PIR is delocalized from the nucleus to the cytoplasm in a proportion of primary melanomas, and that cytoplasmic localization correlates with disease progression." (PMID 20089166, 2010). "Our results show that cytoplasmic delocalization of PIR is characteristic of a subset of advanced stage melanomas, and validates the efficacy of ICA for multiplexed immunofluorescence analysis of target proteins in different cellular models." (PMID 20089166, 2010). "Additionally, pirin controls melanoma cell proliferation by regulating the mitochondrial slow-cycling JARID1B gene." (PMID 39917624, 2025). "Pirin plays a significant influence in melanoma’s responsiveness to MRTF inhibitors." (PMID 40740997, 2025). "Inhibition of pirin or the Rho/MRTF pathway can be employed to prevent melanoma resistance." (PMID 39917624, 2025). "Abnormal pattern of sub-cellular localization of Pirin was observed in a subset of melanomas." (PMID 38033031, 2023).
melanoma (continued). "Moreover, inhibition or decrease of Pirin in melanoma has been shown to diminish cellular migration capacity of melanoma cells." (PMID 37308689, 2023). "Hence, other cellular signaling pathways would appear to be involved in the metastatic activity of Pirin in melanoma cells." (PMID 37308689, 2023). "In addition, we demonstrated that the overexpression of Pirin in both the metastatic melanoma cell lines studied led to a significant decrease in JARID1B gene expression, and that of its target genes E2F1 and c-MYC30,31." (PMID 37308689, 2023). "Together, these results suggest that PIR might modulate melanoma proliferation by targeting the slow-cycling transcriptional regulator JARID1B." (PMID 37308689, 2023). "Together, the data obtained indicated that Pirin could be a useful marker for the metastatic progression of melanoma and that it participates in the proliferation of melanoma cells by regulating the slow-cycling JARID1B gene." (PMID 37308689, 2023). "Focusing on stage I and II melanoma patients, we explored whether Pirin expression might be related to a more aggressive phenotype." (PMID 37308689, 2023). "Moreover, PIR downregulated primary melanocytes were analyzed by RNA sequencing, and the data obtained were validated in human melanoma cell lines overexpressing PIR by functional assays." (PMID 37308689, 2023). "The expression of the Pirin protein in human melanocytic lesions was analyzed by immunohistochemistry on histological sections from 75 nevi and 239 melanomas, and correlated to the clinical data from the nevus and melanoma patients." (PMID 37308689, 2023). "Our results suggest that Pirin expression could represent a good prognostic marker and that it is involved in melanoma cell proliferation through the modulation of JARID1B." (PMID 37308689, 2023). "Activation of the JARID1B promoter was determined through the proportion of cells expressing GFP and significantly, an increase in Pirin expression in MeWO and A2058 melanoma cells led to a significant decrease in JARID1B promoter activation in both metastatic melanoma cell lines." (PMID 37308689, 2023). "Additionally, PIR is highly expressed in tumors including melanomas, lung, cervical or head and neck cancers among others when compared with leukemia, thymoma or diffuse large B-cell lymphoma (DOBC)." (PMID 33557375, 2021). "Pirin has also been shown to play a role in melanoma migration and senescence." (PMID 33921974, 2021). "The function of pirin in general, and specifically in melanoma, remains poorly defined." (PMID 33921974, 2021). "In fact, a significant proportion of cytoplasmatic Pirin was found in metastatic melanoma cells compared to primary melanoma cells, suggesting that this pattern of Pirin localization may represent a cancer progression biomarker." (PMID 33557375, 2021). "Additionally, a previous study showed that knockdown of PIR or treatment with the small molecule markedly suppressed migration of melanoma cells." (PMID 30444038, 2019). "Several intensive researches in the field of cancer show that PIR may act as a relevant role in melanoma and acute myeloid leukemia." (PMID 31299012, 2019). "Pirin is a transcriptional coactivator whose influence on NF-κB dependent transcription via interaction with BCL3 was shown in the case of SNAI2 expression in melanoma cells." (PMID 24390086, 2014). "We performed immunohistochemical analysis of PIR expression in primary samples from normal human tissues and tumors and identified a dislocation of PIR to the cytoplasm in a subset of melanomas, and a positive correlation between cytoplasmic PIR levels and melanoma progression." (PMID 20089166, 2010). "We further demonstrate that this pattern of PIR delocalization is maintained in vitro in primary and established melanoma cell lines using a high density ImmunoCell-Array (ICA) approach, which allows for simultaneous analysis of protein levels and localization in multiple cell lines." (PMID 20089166, 2010).
melanoma (continued). "The pattern of PIR localization observed by IHC in tumour samples is maintained in cultured cell lines, both established and of primary derivation, suggesting they represent a reliable model to study the role of PIR in melanoma progression." (PMID 20089166, 2010). "Moreover, recent evidence suggests that the pirin-MRTF axis may be influenced by upstream oncogenic signalling events, particularly those associated with BRAF or NRAS mutations, prevalent in melanoma." (PMID 40740997, 2025). "In addition, we propose that Pirin could play an important role in modulating the differentiation and proliferative state of melanoma cells by regulating JARID1B gene expression." (PMID 37308689, 2023). "Moreover, they show that such CCG compounds may disrupt Pirin expression, and subsequently interfere with MRTF/SRF/DNA signaling, which has been associated with melanoma metastasis." (PMID 33557375, 2021). "Moreover, delocalization of PIR was identified in melanomas." (PMID 31299012, 2019). "Initial studies indicate that pirin expression and its regulatory role on MRTF are significantly elevated in BRAF-mutant melanoma cells, potentially making these subtypes more vulnerable to concurrent targeting of Rho/MRTF and pirin." (PMID 40740997, 2025). "The downregulation of pirin enhances the inhibitory effect of MRTF signaling, resulting in reduced proliferation and survival of melanoma cells." (PMID 40740997, 2025). "One reported example of this is the description of a small molecule inhibitor of PIRIN, which disrupts Pirin:BCL3 binding, which leads to the inhibition of melanoma cell line migration." (PMID 38195591, 2024). "Interrupting the interaction between Pirin and BCL3 with a Pirin inhibitor has been shown to inhibit melanoma cell metastasis via suppression of snail homolog 2 (SNAI2)." (PMID 38033031, 2023). "We characterized melanoma cells and conducted dimensionality reduction clustering, revealing six distinct cell subgroups: C0 TRPM1+ Melanoma cells, C1 PIR+ Melanoma cells, C2 PHLDA2+ Melanoma cells, C3 ID2+ Melanoma cells, C4 PCLAF+ Melanoma cells, and C5 CD74+ Melanoma cells." (PMID 39781353, 2025). "We studied the proliferation and migration of metastatic melanoma cells in which Pirin was overexpressed and we found this upregulation did not modify migration but rather, it did induce a significant decrease in the proliferation rate of both the melanoma cell lines studied." (PMID 37308689, 2023). "Additionally, there is consistent evidence that bisamide modulates the expression of the transcription factor HSF1 and subsequently inhibits the migration of human melanoma cells WM266.4; however, Pirin participation remains unclear." (PMID 33557375, 2021).
lung carcinoma (17 papers, 2007 to 2026). "Moreover, particulate matter in outdoor air pollution, considered to be a potent oxidative agent and a significant risk factor for respiratory diseases and lung cancer, is associated with Pirin overexpression in human respiratory fibroblasts." (PMID 33557375, 2021). "Further, among the piRNAs that are negatively regulated by RASSF1C, we found that overexpression of piR-35127 and piR-46545 decreased lung cancer and primary epithelial cell proliferation and colony formation." (PMID 36826019, 2023). "Conversely, the mRNA levels for pirin decreased by 90% upon knockout of Nrf2 in the human lung cancer cell line A549, which has constitutively high levels of Nrf2 due to a mutation in Keap1 and hypermethylation of its promoter." (PMID 35204145, 2022). "NRF2, an oxidant responding transcription factor highly active in lung cancer cell lines, can bind to the PIR promoter which contains four functional antioxidant response elements (ARE)." (PMID 33557375, 2021). "Intriguingly, silenced piR-55490 promotes the growth of lung cancer by binding to the mTOR 3′UTR and activating the AKT/mTOR pathway." (PMID 34118972, 2021). "For example, in lung cancer cells piR-55490 was demonstrated to bind with 3′UTR of mTOR mRNA and induce its degradation." (PMID 34295823, 2021). "For example, upregulation of piR-34871 and piR-52200 and downregulation of piR-35127 and piR-46545 by the Ras Association Domain Family Member 1C (RASSF1C) were reported in the lung cancer cell line H1299 and lung tumor tissues." (PMID 34295823, 2021). "The overexpression of piR-55490 in a lung carcinoma xenograft model results in the inhibition of tumor growth." (PMID 34118972, 2021). "The piR-34871 and piR-52200 are up-regulated, while the piR-35127 and the piR-46545 are down-regulated in lung cancer cells." (PMID 31052265, 2019). "Additionally, piR-55,490 inhibits lung carcinoma growth via the mTOR pathway, and piR-651 promotes apoptosis in non-small cell lung cancer (NSCLC)." (PMID 40287690, 2025). "The inhibitory effects of overexpressing piR-35127 and piR-46545 on lung cancer cell migration/invasion are consistent with our previously published work showing overexpression of piR-35127 and piR-46545 decreases lung cell proliferation and colony formation of breast and lung cancer cells." (PMID 36826019, 2023). "This study showed that overexpression of piR-35127 and piR-46545 or knockout of piR-34871 and piR-52200 could promote the proliferation of lung cancer cells." (PMID 36915129, 2023). "We have identified PIWIL1 as a potential regulator of Beta-catenin gene expression and have identified specific piRNAs that appear to function as oncogenes (piR-34871 and piR-52200) and tumor suppressor (piR-35127 and piR-46545) in normal and lung cancer cells." (PMID 33227088, 2020). "However, NRF2 activation/addiction may be involved in other Pirin-independent activities such as cisplatin resistance in lung cancer cells." (PMID 33557375, 2021). "The present study on pirin emerged from our laboratory's ongoing effort to identify unique cellular pathways that are linked to the development of lung diseases, such as COPD and lung cancer, by using gene expression analysis of the airway epithelium of smokers." (PMID 17288615, 2007). "Gastric cancers overexpress piR-651, promoting G2/M arrest evasion; lung cancers feature PMLCPIR enhancing ITGB1-PI3K-AKT signaling; multiple myeloma leverages piR-823 for proliferation; and hepatocellular carcinoma shows PIWIL1 upregulation tied to stemness." (PMID 42022287, 2026). "In non-small cell lung carcinoma, piR-651 increased the expression of Cyclin D1 and CDK4 to promote tumor progression, while piR-55490 inhibited cell proliferation in lung cancer cells by targeting the 3′ UTR (untranslated region) of mTOR mRNA." (PMID 41154843, 2025).
lung carcinoma (continued). "Of note, Pirin levels show a strong correlation with smoking, as well as chronic obstructive pulmonary disease (COPD), which frequently progresses to lung cancer." (PMID 33557375, 2021). "Furthermore, piR-55490 binds the mTOR 3ʹ-UTR, inducing mRNA degradation and repression of lung cancer growth." (PMID 36915129, 2023).